EGFR (epidermal growth factor receptor)
Diseases named in the same sentence as EGFR in open-access papers (continued):
Sharing a sentence is not in itself a finding about the gene and the disease.
tumor (continued). "Here, we have designed an Fc-free tumor-targeted 4-1BB-agonistic trimerbody, 1D8N/CEGa1, consisting of three anti-4-1BB single-chain variable fragments and three anti-EGFR single-domain antibodies positioned in an extended hexagonal conformation around the collagen XVIII homotrimerization domain." (PMID 30442944, 2018). "In 18 samples with less than 32% viable tumor cells, we detected no mutations, but we found KRAS and EGFR mutations in 10 of 80 (13%) patient samples with 32% or more viable tumor cells." (PMID 29673125, 2018). "Hence, radioimmunotherapy based on cetuximab labeled with therapeutic radionuclides appears as a promising strategy allowing the delivery of radiation dose specifically to tumor cells expressing high level of EGFR while sparing normal tissues." (PMID 29777377, 2018). "Additionally, Sym004 has shown superior tumor growth inhibition in a range of xenograft models compared with other monoclonal anti-EGFR antibodies." (PMID 29564747, 2018). "Thus, EGFR inhibition represents a unique treatment strategy as blockade should inhibit further transformation of normal cells, while preferentially killing tumor tissue." (PMID 30018330, 2018). "However, the AZ304 and Cetuximab combination reversed EGFR activation associated with AZ304, and resulted in stronger anti-tumour activity in vitro and in vivo, in RAS wild type CRC cells irrespective of BRAF genetic status." (PMID 29755114, 2018). "Furthermore, intravenous delivery of the selected siRNAs aiming to suppress the expression of ER/BCL2 and ER/ERBB2/EGFR groups of proteins led to a significant retardation in tumor growth in a 4T1-induced syngeneic mouse model." (PMID 29932151, 2018). "While direct application of HAdV5HVR7 to the subcutaneous tumor led to a tumor-to-liver ratio of 300 of the transgene signal, the shielded EGFR-retargeted HAdV5HVR7 resulted in 9200 times higher payload activity in the tumor, in both cases upon intratumoral injection." (PMID 29386504, 2018). "Second, the diagnosis of NSCLC has been more and more relying on small biopsy or cytologic specimens which however sometimes were not of good quality or sufficient number of tumor cells for EGFR mutation testing." (PMID 29164298, 2018). "Additionally, GPRC5A knockout enhances the transformed phenotype in normal and tumor cells through the aberrant activation of the EGFR/STAT3 signaling pathway." (PMID 30417009, 2018). "Indeed, for instance, the prognostic effect of EGFR protein expression was proved by immunohistochemistry using surgically resected tumor tissue in patients with ESCC who underwent surgery alone or surgery and postoperative radiotherapy." (PMID 30115035, 2018). "LB may also help monitor the evolution of resistance mechanisms in the tumor and recent data indicate that LB results may allow re-challenge of previously received anti-EGFR therapy." (PMID 30705875, 2018). "Moreover, there are also some MTFs which are involved in the development and progression of tumours, such as Notch, EGFR and SREBP." (PMID 29615051, 2018). "Thus, in order to develop our mouse experiments, we tested the capacity of 7A7 to bind murine EGFR and to induce tumour regression." (PMID 29552307, 2018). "Next, we assessed the tumor response to cetuximab depending on the level of EGFR expression." (PMID 30373221, 2018). "KRAS mutations in the tumor are a negative predictor of response to EGFR-TKIs or anti-EGFR antibodies." (PMID 29441349, 2018). "We firstly confirmed that DCA activated EGFR in intestinal tumour cells along with time variation." (PMID 29956475, 2018). "We found that afatinib could inhibit tumor growth in PDX models with EGFR amplification (case 141), EGFR overexpression (case 078), or HER2 amplification (case 176)." (PMID 29433585, 2018). "However, in multivariate analysis, only main tumor resection and EGFR-TKI therapy correlated with better survival (P = 0.013 and < 0.001, respectively)." (PMID 29435191, 2018).
tumor (continued). "It is thus plausible that co-existing truncal drivers may be associated with a propensity for primary resistance, while minor clones with additional drivers or resistance-mediating alterations can emerge later after initial tumor response to EGFR TKIs." (PMID 29335443, 2018). "We detected a small but statistically significant overexpression of EGFR in the tumor sample." (PMID 29989001, 2018). "In addition, an orthotopic implantation metastasis model also confirmed that the EGFR inhibitor WZ4002 and silibinin decreased tumor metastasis through the EGFR/LOX pathway." (PMID 29472856, 2018). "A previous study showed that EGFR is involved in the anti-tumor effect of withanolide products." (PMID 30513793, 2018). "Besides improving response rates, significant reducing tumor relapse rates have been a big challenge for EGFR TKIs treatment." (PMID 30533489, 2018). "In both tumors, 89Zr-MEHD7945A accumulated in viable tumor regions with high EGFR expression." (PMID 29899472, 2018). "Indeed, tumor cells addicted to aberrant RTK expression such as MET-amplified GCs and EGFR-mutated NSCLCs were highly sensitive to M-COPA, and these RTKs were effectively downregulated by M-COPA treatment." (PMID 29416720, 2018). "Interestingly, the combination of afatinib and cetuximab, an EGFR-specific antibody, treatment resulted in extensive tumor shrinkage of erlotinib-resistant tumors harboring the T790M mutation in mice but either agent alone was much less effective." (PMID 29765556, 2018). "In agreement with the improved EC50 value of the bivalent α-EGFR-EGFR TM, we could observe an increased anti-tumor effect in experimental mice." (PMID 29876011, 2018). "Overall these data confirmed that the lower specificity of ctDNA observed in EGFR-TKI-resistant NSCLC patients could be partially related to the higher intra-tumor heterogeneity." (PMID 30190486, 2018). "Likewise, affibodies and DARPins engineered to bind human epidermal growth factor 2 (HER2) or EGFR have been used to image tumor xenografts in mice." (PMID 29738555, 2018). "Such a type of molecules could be used alone in tumours addicted to EGFR or to enhance the benefit of TMZ-based chemotherapy in tumours co-expressing EGFR and MGMT." (PMID 30416678, 2018). "Notably, the elevated expression of PD-L1 was observed in EGFR-resistant tumor biopsy compared to pre-treated tumor samples." (PMID 29455663, 2018). "Second, though the EGFR analysis method is wildly used in standard clinical and research practices, heterogeneity of EGFR gene expression in the tumor may influence the results." (PMID 29794775, 2018). "Nevertheless, upon intravenous injection, the shield in combination with the adapter increased the tumor-to-liver ratio for the EGFR+ tumor model by a factor of 2500, and for the HER2+ tumor model 300-fold compared to HAdV5HVR7 alone, in both cases resulting in a tumor-to-liver ratio of >2." (PMID 29386504, 2018). "Whatever the tumour subtypes, metastatic patients with wild-type downstream effectors of the EGFR signalling pathway could reasonably be expected to benefit from anti-EGFR monoclonal antibodies." (PMID 29700411, 2018). "RAC1 activation is thus needed for in vivo tumor growth of human EGFR-mutant NSCLC cell lines." (PMID 30590030, 2018). "The lack of detection of the EGFR p.T790M mutation for patient 2 tumor sample by NGS is more puzzling however, since 6-color digital PCR quantified a 2.8% MAF, well within the detection range otherwise exhibited by NGS in this study." (PMID 30647840, 2018). "On the other hand, hRNase5/ANG originating from endothelial cells or fibroblasts may interact with EGFR on the cell surface of tumor cells which may result in oncogenic transformation via a paracrine pathway." (PMID 30449278, 2018). "This prompted us to investigate whether targeting EGFR with gefitinib alters migration parameters within slice cultures on a per cell basis (n = 6 individual tumor slice cultures)." (PMID 30573757, 2018).
tumor (continued). "And some studies figure out activity ADRB2 can active EGFR signaling pathway for tumor growth." (PMID 30400936, 2018). "Blocking of the EGFR with cetuximab when tumor cells were stimulated with the type 1 cytokine IFNγ and TNFα resulted in the amplification of the production of the T-cell attracting chemokines and resulted in an increased migration of CD4+ and CD8+ lymphocytes in chemotaxis assays in vitro." (PMID 30192802, 2018). "For these 17 patients with paired biopsies, the median HER2 IHC and H scores prior to any treatment were 2+ and 100, while these were 3+ and 240 for the post EGFR TKI tumour samples, respectively, suggesting that EGFR TKI treatment either induced or increased HER2 expression." (PMID 30061586, 2018). "EGFR expression is unchanged comparing mutated vs. non-mutated tumors, and phenotypic features of aggressive tumors, particularly larger tumor size, are not consistently seen." (PMID 30147673, 2018). "Furthermore, treatment of KRAS or EGFR mutant‐driven transgenic LUAD mouse models revealed that cell growth arrest induced by the HCI‐2509 inhibitor resulted in both lower tumor formation and progression in vivo." (PMID 30220105, 2018). "In conclusion, at least 8 loci were shown to be moderately associated with EGFR inhibitor induced severe skin toxicity and none were associated with anti-tumor efficacy." (PMID 30557370, 2018). "Furthermore, TE-4 tumor has moderate EGFR expression, which is easily blocked by treatment dose of cetuximab." (PMID 30373221, 2018). "Even minor disruptions in the EGFR signaling pathway can promote tumor growth." (PMID 29876011, 2018). "Despite the similarities in gene expression between these models, there are clear differences in the oncogenic potential of IGFIR and EGFR in the mouse lung as tumor onset occurs much more rapidly in the mutant EGFR models (4–8 weeks versus 8–9 months in SPC-IGFIR mice)." (PMID 30412601, 2018). "Our results suggest that Prp8 could be a specific target in tumours driven not only by Ras, Notch and EGFR but, potentially, by other receptor tyrosine kinases that signal through Ras and downstream pathways." (PMID 30333215, 2018). "EGFR mutation status was evaluated in 77% of the chemotherapy cohort and 63% of the erlotinib cohort, when evaluable specimens (tumor or plasma) were available; however no EGFR mutations were detected in any sample." (PMID 29558888, 2018). "It is not clear whether EGFR-TKI has a previously undescribed direct effect on platelets or the activation signal from cancer cells to platelets is decreased as a result of reduced tumor burden after EGFR-TKI." (PMID 30192878, 2018). "Finally, due to the finding of TrkB as overexpressed in SCC, we performed in vitro and in vivo validation of the role of this factor in tumor progression, also focusing on its interaction with the EGFR pathway." (PMID 29581842, 2018). "The basis for this post-progression prolongation of survival comes from the continued application of selective pressure on EGFR TKI-sensitive tumor subclones, thereby preventing regrowth and reducing the risk of rapid progressive disease once treatment is withdrawn." (PMID 29632655, 2018). "We then compared the EGFR expression in matched pairs of tumor and normal adjacent tissue samples." (PMID 29989001, 2018). "We hypothesised that BAG3 may regulate tumour cell proliferation by regulating EGFR signalling networks." (PMID 29644001, 2018).
tumor (continued). "The biologic basis for the worse outcome with anti-EGFR based therapy in right-sided tumours is so far unknown and even classification of tumours according to the Consensus Molecular Subtypes (CMS) could not clarify this issue." (PMID 29298682, 2018). "Although this fraction was reportedly small, representing 4.5% of a cohort with 350 GBMs, it introduces the risk of misidentifying tumour cells without the IDH mutation/EGFR amplification as stromal cells." (PMID 28173797, 2017). "Furthermore, a recent study showed that NSCLC cell lines changed the cellular response to growth factors as well as inhibitors of EGFR signalling when cultivated as 3D spheroids, that better mimicked the natural tumour microenvironment." (PMID 28417948, 2017). "Moreover, the tumour growth inhibition of mice treated with Anti-EGFR-CIL-miR-135a was much higher than that of mice treated with miR-135a and LCL-miR-135a." (PMID 28729631, 2017). "In the anti-EGFR-GN+NIR-PTT group, the PA signal amplitude and bioluminescence activity of tumors remarkably decreased after second and third treatments, which may selectively reflect EGFR-positive tumor cell damage or tumor vascular insult." (PMID 29156817, 2017). "EGFR was less tumor-specific due to regular expression in normal tissues." (PMID 28841839, 2017). "The data we have present also indicate that it may not only be the KRAS and EGFR status itself, but rather the quantitative amount of cfDNA derived from tumor that influences the disease behavior." (PMID 28382702, 2017). "Second, we attempted to translate this technology to clinical diagnosis, and demonstrated that mutant plasma EGFR (pEGFR) concentration determined by ddPCR analysis could achieve a concordance of 86.73% with tumor EGFR (tEGFR) status." (PMID 28061461, 2017). "Thus, the limit of detection (LOD) of the T790M mutation by Idylla was below 10.7% allelic frequency (reported LOD for the EGFR therascreen Pyro kit) in two specimens with 50% tumor cells." (PMID 29262544, 2017). "These in vitro data prompted us to hypothesize that the regulation of EGFR-dependent tumor growth in vivo is predominantly driven by signaling through the ERK1/2 pathway." (PMID 29268862, 2017). "Nevertheless, when testing EGFR mutations in the plasma ctDNA, the sensitivity of ARMS was only 48.2–67.4% compared to the matched tumor tissue, in spite of a high specificity of 93.5–99%, which indicates that the blood-based EGFR mutation testing method is limited by a relatively low sensitivity." (PMID 28829813, 2017). "Furthermore, these Nb constructs secreted from NSCs were designed to target GBM tumor tissues, which show an enhanced EGFR expression." (PMID 29163515, 2017). "And it has been a standard method to detect EGFR gene status in tumor tissue." (PMID 28000387, 2017). "Theoretically, bevacizumab in combination with EGFR-TKIs might improve the anti-tumor effect because they target different tumor growth pathways (angiogenesis and EGFR activity, respectively)." (PMID 28977977, 2017). "Statistical results showed that gelsolin expression in PCa was associated with disease status, tumor grade, cigarette smoking, serum PSA level, lymphovascular infiltration and the expression of androgen receptor, AKR1C2 and epidermal growth factor receptor (EGFR)." (PMID 29100377, 2017). "The functions of EGFR and YAP in cell survival and tumor promotion are similar; thus, we examined whether EGFR could be regulated by YAP." (PMID 28425446, 2017). "The difference in PFS indicated that local treatments, which did not focus on all tumor sites, did not have a survival advantage for patients with EGFR-sensitive mutations treated with MWA plus EGFR-TKIs." (PMID 28915624, 2017). "The addition of SGX523 resulted in loss of EGFR-MET heterodimer and reduction in phosphorylated ERK in the H1975L858R/T790M cells and derived tumours, in agreement with this hypothesis." (PMID 28141869, 2017).
tumor (continued). "In our patients set, EGFR staining was positive in 45% of the tumor samples." (PMID 29088795, 2017). "By combining current therapies with the use of EGFR antagonists, enhanced anti-tumor immune responses in cancer patients may be seen." (PMID 28970798, 2017). "EGFR is another important protein in relation to tumor development." (PMID 29282071, 2017). "There was insufficient tumour sample for EGFR testing in 9/22 (40.9%) patients." (PMID 28367333, 2017). "The incidence of EGFR positivity in epithelial tumors varies by tumor type." (PMID 29379438, 2017). "Its anti-tumour rate of Anti-EGFR-CIL-miR-135a was 60% at 12 days post-injection." (PMID 28729631, 2017). "Interestingly, maintaining anti-EGFR therapy while re-introducing chemotherapy stopped tumor growth and stabilized the disease." (PMID 27852040, 2017). "Cetuximab is an immunoglobulin G subclass 1 (IgG1) monoclonal antibody (mAb) targeting the EGFR by preventing its ligand-mediated activation and dimerization, and it thus inhibits tumor cell proliferation and stimulates proapoptotic pathways within the tumor cell." (PMID 28536670, 2017). "In both IHC assays, the percentage of tumors with PD-L1 expression on ≥1%, ≥5% and ≥50% of tumor cells was similar in groups of patients with and without EGFR gene mutations." (PMID 28969070, 2017). "One of the processes to enhance tumor angiogenesis consists in the activation of the EGFR pathways." (PMID 29276515, 2017). "All these strategies aim at predicting the sensitivity of the tumor cells to EGFR-TKIs." (PMID 28671975, 2017). "However, it has previously been reported that miR-223 was able to reverse tumor resistance of EGFR tyrosine kinase inhibitors (TKIs)." (PMID 28915663, 2017). "Other CT features such as tumor size, cavitation, air-bronchogram, lobulation and spiculation were not correlated with EGFR mutation." (PMID 28068946, 2017). "We agree it is difficult to draw certain conclusions given the evidence of today, though in our opinion, different driver mutations (such as EGFR or KRAS mutations or ALK or ROS1 rearrangements, like in our cases 4 and 6) probably quite strongly support synchronous/metachronous tumours." (PMID 28347348, 2017). "Importantly, a clinical trial on EGFR-targeted intraoperative optical tumor imaging was recently published, and EGFR-directed PET-imaging has been demonstrated in preclinical studies." (PMID 28841839, 2017). "However, as the EGFR is also ubiquitously expressed on healthy tissues, such modes of action would only be able to explain for the clinical efficacy of treatment on tumor cells that express an elevated level of the target molecule." (PMID 28970798, 2017). "Nimotuzumab was able to kill EGFR+ tumor cells by NK cell-mediated ADCC." (PMID 28674498, 2017). "In keeping with the concept of mutual exclusiveness of classic mutated driver genes, none of the four EGFR-positive patients who also underwent ALK-testing had an ALK-translocated tumor." (PMID 29100434, 2017). "In the present study we show that celecoxib enhances the antitumor efficacy of cetuximab in CRC and reduces colon cancer stem cells tumor subpopulation, supporting that the combination of EGFR and COX-2 inhibitors could improve current mCRC therapies." (PMID 28423516, 2017). "In addition, PGE2 can transactivate EGFR-mediated signaling networks that confer an aggressive phenotype to tumor cells." (PMID 28415726, 2017). "The metalloprotease domain of ADAM9 can cleave the heparin-binding epidermal growth factor like growth factor (HB-EGF) precursor to yield soluble HB-EGF29, thereby activating epidermal growth factor receptor (EGFR) signal transduction to promote tumor growth and angiogenesis." (PMID 29118335, 2017). "Univariate analysis of the PFS data showed that female patients and those with an ECOG PS of 0, an EGFR-sensitive mutation, no smoking history, and a tumor response had a significantly longer median PFS (P = 0.037, 0.01, 0.035, 0.007, and 0.000, respectively)." (PMID 29156802, 2017).